BDNF (brain derived neurotrophic factor)
Diseases named in the same sentence as BDNF in open-access papers (continued):
Sharing a sentence is not in itself a finding about the gene and the disease.
depression (continued). "Depression-like, anxiety-like, and cognitive impairment caused by indoxyl sulfate were accompanied by indoxyl sulfate CNS accumulation, impaired neuronal cell survival and neurogenesis, disturbed BDNF, serotonin, corticosterone, and REST expression, oxidative stress, and neuroinflammation." (PMID 33621199, 2021). "Therefore, in our present study, we used a chronic unpredictable mild stress- (CUMS-) induced depression model to investigate whether the antidepressant-like effects of CUR are associated with the activation of the PGC-1α/FNDC5/BDNF pathway." (PMID 34950248, 2021). "The neurotrophic hypothesis of depression is heavily based on the correlation between lower levels of BDNF and a higher frequency of depression, depressive symptomatology, neuronal loss, and cortical atrophy, and the restoration of the BDNF effect is linked to antidepressants." (PMID 33643008, 2021). "This suggests that reduced BDNF levels may be associated with the diagnosis of depressive disorder." (PMID 34576215, 2021). "However, a study performed in a Chinese population indicated that this polymorphism could be involved in the pathogenesis of depression presented in people with T2D, by decreasing serum levels of BDNF." (PMID 33269104, 2020). "Furthermore, some findings suggested that lower plasma BDNF levels might be associated with the symptomatic severity in any type of anxiety disorder, major depressive disorder, and schizophrenia." (PMID 33047489, 2020). "Many past studies measured the serum BDNF levels in MDD patients and identified its association with depression but none of them were evaluated for their accuracy in diagnostic or predictive purpose." (PMID 32085720, 2020). "Serum BDNF may act as a marker of predisposition to depression." (PMID 33255237, 2020). "Moreover, oxidative damage could affect various genes such as CREB1 and BDNF, associated with neuronal regeneration, depression, and cognition." (PMID 32841551, 2020). "Finally, we only investigated the association in BDNF gene with the psychopathology of depression." (PMID 32869548, 2020). "Furthermore, BDNF levels have been linked with psychotic depression, age at onset and anxiety." (PMID 31127089, 2019). "However, it remains unclear whether inflammation-induced changes in BDNF levels in the brain are associated with the formation of depression-related behaviours and whether this can be reversed therapeutically." (PMID 31053872, 2019). "Indeed, according to the “neurotrophic hypothesis of depression,” the psychopathology is associated with the reduction of brain BDNF levels and antidepressant treatments alleviate depressive symptoms increasing its levels." (PMID 30804991, 2019). "Therefore, our purpose was to investigate if high cadence cycling altered cognition and depression symptoms and whether potential changes are influenced by the presence of BDNF polymorphism." (PMID 31197095, 2019). "Patients with depression generally present neurodegeneration and smaller hippocampal and prefrontal cortex volume and such reductions are not only due to neuronal death, but also caused by decreased neuroplasticity and neurogenesis secondary reduced expression of neurotrophic factors, such as BDNF." (PMID 31231276, 2019). "Moreover, BDNF negatively associated with depression among acne vulgaris patients." (PMID 31234814, 2019). "On the other hand, low levels of BDNF are associated with malfunctioning cognitive learning, depression, and conditions for nerve degradation, and research has shown that there is a relationship between increased aerobic exercise in the volume of the hippocampus with increasing BDNF levels." (PMID 31317694, 2019). "Finally, estrogen may also play a role as an anti-depressant, because of its stimulating effect on then brain-derived neurotrophic factor (BDNF), an important neuroprotective and growth factor agent, found to be deficient in depression." (PMID 31581598, 2019).
depression (continued). "BDNF modulates neurotransmitters and receptor activity and is involved in the activation of serotonergic, noradrenergic, and dopaminergic pathways and neurogenesis in the hippocampus and cerebral cortex, which are implicated in the neurobiology of psychiatric disorders, including depression." (PMID 29623232, 2018). "Moreover, the loss of BDNF was suggested play a major role in the pathophysiology of depression." (PMID 30337869, 2018). "Together with our previous results, the current findings suggest that apart from immune activation, the BDNF-related imbalance of Copine 6 expression in the brain might play a crucial role in stress-associated depression-like behaviors and synaptic plasticity changes." (PMID 30429764, 2018). "Low levels of BDNF may predispose to neuronal degeneration, neuronal atrophy and decreased dendritic numbers, thus leading to low synaptic activity and clinical symptoms of depression." (PMID 30034974, 2018). "We systematically reviewed the evidence for altered expression of BDNF and its receptor TrkB in the brain of rats exposed to a long-term (more than 2 weeks) social isolation, which is used to model behavioral and neurobiological phenotype associated with schizophrenia and depression in humans." (PMID 28620285, 2017). "Deletion of the BDNF gene causes dendritic degeneration and neuronal loss, and decreased BDNF levels are associated with cognitive impairments in patients with Parkinson’s disease, Alzheimer’s disease, depression, and many other neurological and psychiatric disorders." (PMID 29179434, 2017). "Furthermore, a decrease in BDNF level can lead to a decrease in hippocampal volume and number of nerves, dendritic reconstruction, loss of glial cells, increasing neurotoxicity, and increasing susceptibility to depression." (PMID 28706741, 2017). "Moreover, further study with larger statistical power than that in previous studies is needed to examine whether Val66Met in BDNF gene is associated with late-life depression." (PMID 29387021, 2017). "More specifically, the relationships of the BDNF Val66Met polymorphism with cognition, emotion and even with several brain disorders including major depression, epilepsy, schizophrenia, and stroke are suggested to be mediated by its effects on the alterations in gray and white matters." (PMID 28824404, 2017). "There is evidence that reduced BDNF secretion, as well as altered functional and structural connectivity of prefrontal cortical areas may be linked to Met carriers, which may presumably render greater neurocognitive vulnerability to depression." (PMID 28769852, 2017). "However, whether COX2 and BDNF share a common pathway in the pathophysiological processes underlying cognitive dysfunctions observed in depression remains unclear." (PMID 28415673, 2017). "However, Val66Met in the BDNF gene was associated with late-life depression." (PMID 29387021, 2017). "Therefore, increased BDNF–TrkB signaling in NAc may play a causative role in the pathophysiology of depression." (PMID 28769056, 2017). "Both depression and the Met allele of the Val66Met polymorphism on the gene coding for BDNF may be accompanied by reductions in structural and functional connectivity of the hippocampus and prefrontal cortex, and BDNF concentrations in serum have been linked to depressive disorders." (PMID 28769852, 2017). "Thus, this naturally occurring genetic variant of the BDNF gene may contribute to a genetic predisposition for depressive disorder." (PMID 28928987, 2017). "In addition, BDNF plays a role in processes such as neuronal maturation, synapse formation and synaptic plasticity, among others, in the brain, and has also been implicated in a number of psychiatric disorders such as depression." (PMID 27852063, 2016).
depression (continued). "Disruption of either BDNF or endocannabinoid signaling is associated with an overlapping set of neurologic and psychiatric diseases, and both systems are currently major targets for the development of novel therapeutics, particularly in relation to depression, anxiety, autism, and schizophrenia." (PMID 25938134, 2015). "The results of our study and those of others raise the possibility that serum BDNF levels may point toward new therapeutic opportunities, and suggest that BDNF should be evaluated as a possible biomarker for risk prediction and monitoring response to treatment for antepartum depression." (PMID 25886523, 2015). "In addition to depression, the BDNF system is implicated in some other neuronal dysfunctions, like Alzheimer’s disease, so it is possible that TMP may also produce effects in these disorders, and this needs further study." (PMID 25618406, 2015). "Given that depression and cognition are intrinsically linked to similar brain structures such as the hippocampus, extrapolating those findings suggest the likelihood that risk or severity of depression could also be influenced by this common functional polymorphism of BDNF." (PMID 25806005, 2015). "However, the view that depression is associated with low levels of BDNF and that BDNF is necessary for antidepressant effects may be too simplistic." (PMID 25932008, 2015). "Interestingly, and in line with the neurotrophin hypothesis, some studies show that the increase in BDNF following ECS is associated with a decrease in depression-like behaviors." (PMID 26529101, 2015). "Hence, we speculate that any misclassification in maternal antepartum depression status is generally likely to have resulted in an underestimation of the true magnitude of association between lower BDNF levels and antepartum depression risk." (PMID 25886523, 2015). "In addition, the relatively small size of some studies, particularly those failing to document associations of BDNF levels with depression, may have had limited the statistical power for testing their study hypotheses." (PMID 25886523, 2015). "BDNF Val66Met affects activity-dependent neural release of BDNF and hippocampal activity, and a recent study suggests that this polymorphism may increase susceptibility to depression in people with a history of early trauma through neural mechanisms involving reduced gray matter in the hippocampus." (PMID 26230319, 2015). "We investigated BDNF methylation levels at two CpG islands within promoters I and IV, using DNA derived from buccal tissue, and determined whether there was an association with clinical levels of depression at baseline, as well as chronic depression." (PMID 26285129, 2015). "Furthermore, in tests for depression-like behaviors, such as the learned helplessness or forced swim tests, hippocampal BDNF infusions produce antidepressant-like effects, while targeted hippocampal deletion of BDNF was sufficient to cause depression-like behaviors." (PMID 25932008, 2015). "Furthermore, synaptic dysfunction, hyperactivity of the hypothalamic-pituitary-adrenal (HPA) axis, and expression changes or polymorphisms of brain-derived neurotrophic factor (BDNF) may also be associated with depression." (PMID 25875952, 2015). "The other biochemical effects induced by zinc deficiency that may be involved in the pathomechanism of depression include a reduction in the protein level of brain-derived neurotrophic factor (BDNF), tropomyosin-related kinase B (TrkB) receptor and GPR39 Zn2+-sensing receptor." (PMID 24748223, 2014). "It was hypothesized that biological changes associated with BDNF levels are larger in patients with a greater severity of depression based on meta-analyses that have shown significant differences between the effects of antidepressants and placebo on changes in HAMD or MADRS scores in such patients." (PMID 24663244, 2014).
depression (continued). "However, considering the emerging data on complexity of BDNF pathway, further findings are needed to better understand whether BDNF is a real causal factor for the depression-obesity association." (PMID 25386150, 2014). "The cellular and molecular alterations underlying anxiety disorders and depression are partially understood, and involve reductions in synaptic densities in the hippocampus, deficits in serotonergic and noradrenergic neurotransmission, and reduced BDNF signaling." (PMID 25202234, 2014). "An additional point of attention is that depression research showed that BDNF effects are diverse in the brain, might be regionally specific, and subsequently, that the BDNF gene has been associated with various phenotypes that are interrelated with loneliness such as trait anxiety and depression." (PMID 24647525, 2014). "In fact, depression is often associated with cardiovascular disease, stroke, dementia, and Alzheimer, and it is characterized by anticipated gene expression changes (e.g., downregulation of the brain derived neurotrophic factor (BDNF)), which usually occurs in the aged brain." (PMID 24349610, 2013). "Regarding genetic causes, certain polymorphisms in genes related to the serotonergic system as the serotonin transporter, the brain-derived neurotrophic factor, the monoamine oxidase A, or the tryptophan hydroxylase 1, may increase the risk for depression or the vulnerability to stress." (PMID 23862076, 2013). "In addition to the regulation of BDNF production, previous studies have associated neurogenesis with the beneficial actions of specific antidepressants, suggesting a connection between decreased hippocampal neurogenesis and depression." (PMID 23805233, 2013). "Epidemiological studies on aging found gender-specific associations also with other biomarkers, such as plasma level of brain derived neurotrophic factor and personality traits linked to depression, although it is unknown whether this may have a relationship with oxidative stress." (PMID 23776478, 2013). "This said, there does seem to be reason to suppose that the BDNF mutation may contribute to depression in certain populations, including the elderly as well as individuals that might have encountered early life stressors, particularly those that entailed neglect." (PMID 23824678, 2013). "However, the clinical significance of the effect of BDNF levels on depression and the impact of Val66Met polymorphism remain unclear in T2DM patients with depression." (PMID 23968401, 2013). "How could the BDNF Val66Met polymorphism influence depression in the T2DM subjects?" (PMID 23968401, 2013). "In conclusion, our current study demonstrated that the presence of the functional BDNF Val66Met polymorphism was associated with depression in T2DM by decreasing the serum BDNF levels, suggesting that increased BDNF levels may be a therapeutic potential in depression patients with T2DM." (PMID 23968401, 2013). "Thus, the conditional knock out studies fail to support the hypothesis that loss of BDNF in male animals results in behavioral manifestations of depression." (PMID 22912626, 2012). "Dysfunction in BDNF signaling may be implicated in the pathophysiology of anxiety and depression." (PMID 22163304, 2011). "Furthermore, both COMT Val158Met and BDNF Val66Met polymorphisms have been shown to be involved in the development of depressive disorders and, there is a well known interplay between pain and depression." (PMID 21049025, 2010). "In addition to the regulation of striatal neuron differentiation, corticostriatal BDNF signaling has been implicated in the etiology and treatment of neurodegenerative and neuropsychiatric disorders including drug addiction, depression, schizophrenia, and Huntington's disease (HD)." (PMID 19390590, 2009).
depression (continued). "Therefore, the BDNF hypothesis postulates that a loss of BDNF is directly involved in the pathopysiology of depression, and that its restoration may underline the therapeutic efficacy of antidepressant treatment." (PMID 21152205, 2009). "Consistent with clinical observations showing decreased BDNF protein levels in the hippocampus and medial prefrontal cortex of patients with major depressive disorder, our experiments revealed that LPS treatment significantly suppressed BDNF expression." (PMID 41556446, 2026). "BDNF is known to play a key role in the pathophysiology of depression and related mood and anxiety disorders." (PMID 40855004, 2026). "Neurogenic biomarkers—including brain-derived neurotrophic factor (BDNF), Ki-67, doublecortin (DCX), and hippocampal volume—have shown consistent associations with depression severity." (PMID 41586064, 2026). "EA produces concurrent analgesic and antidepressant effects by modulating the CREB-serotonin-BDNF signaling axis in the anterior cingulate cortex and spinal cord regions in murine models of chronic neuropathic pain comorbidity with depression-like behaviors." (PMID 41517678, 2026). "Nonetheless, exploratory results highlight BDNF as a potential mediator, warranting further study on its role in postretrieval extinction effects in depression." (PMID 41604295, 2026). "Considering the well‐documented involvement of neurotrophic factors in neuronal plasticity and depression pathophysiology, we next quantified brain‐derived neurotrophic factor (BDNF) expression." (PMID 41556446, 2026). "BDNF rs6265 was associated with catastrophising (p = 0.044), OPRM1 rs1799971 with anxiety (p = 0.030), and MAOA rs1137070 with depression (p = 0.020)." (PMID 41460692, 2026). "For example, the hippocampus shows particularly robust BDNF suppression in depression models, while the nucleus accumbens demonstrates dopaminergic dysfunction specifically relevant to anhedonia." (PMID 41438694, 2026). "BDNF is a key regulator of neuroplasticity and neuronal survival as well, and its role in depression is complex and bidirectional." (PMID 40855004, 2026). "In another study, Amuc_1100 restored BDNF and tropomyosin receptor kinase B (TrkB) expression in the hippocampus and cortex, alleviating anxiety and depression induced by an antibiotic cocktail." (PMID 41251175, 2026). "On the other hand, stress and depression themselves downregulate BDNF expression, particularly in the hippocampus and prefrontal cortex, which exacerbates depressive symptoms and hinders recovery." (PMID 40855004, 2026). "BDNF, essential for neuronal survival and synaptic modulation, is consistently downregulated in depression, contributing to decreased neuroplasticity." (PMID 41535967, 2026). "The current research focus is on the HPA axis and BDNF, and the integrated treatment idea to solve depression and T2DM at the same time has the potential to change in chronic disease management and clinical practice." (PMID 42040575, 2026). "Other non‐imaging primary brain health outcomes were: EEG (27 studies, 7.4%); BDNF levels (11 studies, 3.0%); cognitive testing (one study, 0.3%); the Beck depression score (one study, 0.3%); and serum τ and amyloid β levels (one study, 0.3%)." (PMID 41084412, 2026). "Dysregulation of this pathway, particularly involving key nodes like BDNF, RAF1, and downstream effectors such as JUN, has been increasingly implicated in the pathophysiology of Major Depressive Disorder." (PMID 41438694, 2026). "CSP can alleviate depression by increasing BDNF levels, improving nerve nutrition and angiogenesis, and promoting hippocampal nerve nutrition." (PMID 40202374, 2025). "Downregulation of BDNF gene expression has been reported in the mPFC of the mouse model of depression." (PMID 39609371, 2025).